IRS1 (insulin receptor substrate 1)
Diseases named in the same sentence as IRS1 in open-access papers (continued):
Sharing a sentence is not in itself a finding about the gene and the disease.
Hyperinsulinemia (106 papers, 2006 to 2026). An increased concentration of insulin in the blood. "Inactivating mutations result in hyperinsulinemia and upregulate the IRS1 and PI3K-Akt pathway, causing increased lipogenesis." (PMID 40981175, 2025). "This phenomenon is associated with compensatory hyperinsulinemia, in which insulin signaling through the IRS-1/PI3K/Akt pathway is impaired in muscle, liver, and adipose tissue, which favors lipid accumulation and peripheral lipotoxicity." (PMID 41471698, 2025). "The resulting compensatory hyperinsulinemia is caused largely by phosphorylation of the insulin receptor and insulin receptor substrate-1 (IRS-1), which reduces the efficiency of insulin signaling." (PMID 37886939, 2023). "The following is the specific mechanism of action: at the transcriptional level, hyperinsulinemia causes IRS1 protein degradation and inhibits IRS2 production." (PMID 36589630, 2022). "Hyperinsulinemia caused by overnutrition also activates mTORC1 via the insulin receptor substrate 1 (IRS1)-PI3K-Akt/ protein kinase B (PKB) pathway, which negatively regulates autophagy." (PMID 33255983, 2020). "Decreased IRS1 in the liver can cause the fasting hyperinsulinemia often observed in patients with NAFLD, since higher serum insulin levels are needed to suppress gluconeogenesis in the liver." (PMID 29749571, 2018). "This suggests that in NAFLD, hyperinsulinemia, and hepatic insulin resistance result from decreased hepatic IRS1 expression associated with hepatic necroinflammatory activity." (PMID 29749571, 2018). "The presence of these metabolites leads to high serine phosphorylation of IRS-I (insulin receptor substrate-1) thus reducing insulin signaling and causing hyperinsulinemia." (PMID 28798859, 2017). "The hyperinsulinemia was associated with hepatic insulin signaling protein dysregulation, as shown by the downregulation of IR-β, IRS-1, and Akt-1." (PMID 26718412, 2016). "In summary, this report confirms the association of the major C-allele of rs2943641 near IRS1 with increased risk of T2D, fasting- and glucose-stimulated hyperinsulinemia and impaired insulin sensitivity." (PMID 21917432, 2012). "Notably, the IRS1 rs2943641 polymorphism, located downstream of the IRS1 gene, has been associated with increased fasting hyperinsulinemia and reduced insulin sensitivity." (PMID 38694942, 2024). "Given that hyperinsulinemia is likely to cause drug resistance, metformin can lead to variations in the phosphorylation position of IRS‐1 to evoke insulin sensitivity; thus, this shift may be critical to metformin‐mediated sensitization of oxaliplatin." (PMID 32248666, 2020). "This may be caused by the downregulation of Irs2 induced by hyperinsulinemia in both the PP and PV zones of the liver, coupled with the higher Irs1 expression levels in the PV zone." (PMID 27708333, 2016). "In insulin-resistant states, impaired IRS-1/PI3K/Akt metabolic signaling triggers compensatory hyperinsulinemia." (PMID 41601879, 2026). "Hyperinsulinemia can also downregulate signaling of the insulin receptor at the level of effector molecules, disrupting phosphorylation of Insulin Receptor Substrate-1 (IRS-1), Phosphatidylinositol 3-kinase (PI3K), and Protein Kinase B (Akt)." (PMID 41009753, 2025). "Hyperinsulinemia can also downregulate signaling at the level of effector molecules, disrupting phosphorylation of IRS-1, PI3K, Akt and PKC." (PMID 40013621, 2025). "Concurrently, diets rich in refined carbohydrates can exacerbate hyperinsulinemia by influencing the expression of genes such as IRS1 and GCKR, further complicating the metabolic landscape in individuals who are predisposed to IR." (PMID 40278374, 2025). "In this scenario, carriers of the C allele for the rs2943641 SNP, which is adjacent to the insulin receptor substrate 1 (IRS1) gene, have been associated with IR with hyperinsulinemia in Europeans." (PMID 40278374, 2025).
Hyperinsulinemia (continued). "DIO rats had lower hepatic JAK2 protein levels but higher IRS-1 levels than control rats due to hyperinsulinemia." (PMID 37189668, 2023). "Hyperinsulinemia can reduce intracellular levels of IRS1 and IRS2 genes in cell culture models and mouse tissues." (PMID 36589630, 2022). "Insulin also promotes phosphorylation of IRS-1 on Ser307 in human skeletal muscle during a hyperinsulinemic-euglycemic clamp suggesting that chronic hyperinsulinemia further induces insulin resistance." (PMID 34943997, 2021). "Due to the abundant expression of Irs1 in the PV zone, insulin signaling is considered to be rather enhanced in the presence of hyperinsulinemia despite the downregulation of Irs2, resulting in increased lipogenesis and development of steatosis." (PMID 33923817, 2021). "Like the LIRKO mice, liver-specific Irs1/Irs2 double-knockout (LIrs1/2DKO) mice also exhibited impaired glucose tolerance with hyperinsulinemia and impaired suppression of hepatic glucose production." (PMID 33923817, 2021). "The results and our assumptions about a possible metabolic syndrome were also backed by significant hyperinsulinemia and a decrease in insulin receptor substrate 1 level in the liver." (PMID 32927823, 2020). "The data for IRS-1 also corroborated the increased hyperinsulinemia in the WD+GWI group observed earlier." (PMID 32927823, 2020). "Recent studies show that diabetogenic factors, such as free fatty acid (FFA), TNF-α and hyperinsulinemia, increase the serine phosphorylation of IRS-1, and ser307/612/632 were identified as phosphorylated sites." (PMID 30871060, 2019). "Insulin resistant IRS-1−/− mice demonstrated insulin secretory defects, hyperplastic islets, hyperinsulinemia, and normoglycemia." (PMID 26937254, 2016). "In contrast, in the PV zone, where Irs1 is abundantly expressed, insulin signalling is rather enhanced in the presence of hyperinsulinemia despite the downregulation of Irs2, resulting in the increased lipogenesis and development of steatosis." (PMID 27708333, 2016). "The actions of 2 and 5 FATP are dose-dependent and bimodal, and they are mediated by insulin receptor substrate-2 (IRS-2) under low concentrations of insulin and insulin receptor substrate-1 (IRS-1) during states of hyperinsulinemia." (PMID 25789328, 2015). "Hyperinsulinemia is known to increase mTOR/p70 S6K pathway and increased IRS-1/2 serine phosphorylation indicating insulin resistance state of a tissue." (PMID 24460834, 2014). "Ultimately, the sums of all of these processes appear to be mediated via an imbalance of insulin substrates, where hypoinsulinemia is characterized by excessive IRS-2 signaling, and hyperinsulinemia with predominant IRS-1 signaling." (PMID 22745692, 2012). "Based on the ChIP-seq data, the same FOXO1 feedback loop influencing Igf1r, Insr, Irs1, and Irs2 may be present in other tissues experiencing hyperinsulinemia conditions." (PMID 40105689, 2025). "Chronic hyperinsulinemia induces serine phosphorylation of insulin receptor substrate-1 (IRS-1), thereby inhibiting the downstream activation of the PI3K–AKT–mTOR axis, a pivotal signaling cascade involved in immune cell metabolism, proliferation, and survival." (PMID 40564061, 2025). "Alternatively, hyperinsulinemia may differentially activate insulin receptor substrate-1 (IRS-1) versus IRS-2 in NAFLD." (PMID 37242206, 2023). "Concerning this phosphorylation, it has also been reported that hyperinsulinemia may result in the permanent phosphorylation of IRS-1 on Ser307, resulting also in the hampering of insulin signaling." (PMID 38247463, 2023). "Chronic hyperinsulinemia induces IRS1 hyperactivity in neurons and eventually leads to IR with its associated pathogenic effects, including mitochondrial dysfunction, oxidative stress, abnormal glucose metabolism, inflammation, protein aggregation, and defective neurogenesis." (PMID 32192190, 2020).
Hyperinsulinemia (continued). "In short-term lipid infusion, hyperinsulinemia may stimulate activation of IRS-1 and up-regulates the activation of Akt, which promote a metabolic switch characterized by increased glycolysis while impairing mitochondrial fatty acid oxidation." (PMID 30089498, 2018). "Since the phosphorylation of IRS1 at Ser302 is substantially induced by hyperinsulinemia, the lower insulin level may also contribute to the less phosphorylation of IRS1 at Ser302 in Cpt1b+/− mouse muscle." (PMID 25309812, 2014). "Additionally, serine phosphorylation of the insulin receptor and IRS-1 and -2 is enhanced by chronic hyperinsulinemia that negatively modulate insulin signaling via activation of TNF-α." (PMID 18570670, 2008). "Moreover, bearing in mind that insulin also stimulates growth and triggers many signaling cascades, hyperinsulinemia boosts the serine phosphorylation of IRS-1 (Ser375), MEK1/2, ERK1/2, S6K1, and PI3K p110a, decreases tyrosine phosphorylation IRS-1, and the p85 subunit of PI3K is not changed." (PMID 35454166, 2022). "Therefore, chronic hyperinsulinemia in high-salt-fed-Dahl S rats might as well enhance serine phosphorylation on IRS-1 and/or IRS-2 and explain insulin resistance in Dahl S rats." (PMID 18570670, 2008). "Excess nutrients and hyperinsulinemia induce mTORC1 and S6K1 overactivation, which further downregulate IRS1 transcription and promote IRS1 degradation." (PMID 36224569, 2022). "Constant high levels of BCAAs persistently activate the mTORC1 signaling pathway, leading to IR with the serine phosphorylation of insulin receptor substrate 1 (IRS-1), which occurs in response to persistent aminoacidemia or hyperinsulinemia." (PMID 34828808, 2021). "Based on IRS1 and IRS2 expression in the liver, we aimed to investigate the relationship between NAFLD and impaired glucose metabolism, focusing on hyperinsulinemia, insulin resistance, and postprandial hyperglycemia." (PMID 29749571, 2018). "On the other hand, the phosphorylation level of Akt is increased in the PV zone, because of the intact expression levels of Irs1 in the absence of suppression by hyperinsulinemia." (PMID 33923817, 2021). "Most importantly, subcutaneous injection of hyperinsulinemic Wistar rats with rapamycin (4 mg/kg b.w.)prevented the hyperinsulinemia-induced serine phosphorylation of IRS-1 and the reduction in the IR/IRS-1/PI3K/Akt signaling pathway in muscle and liver tissues." (PMID 32230718, 2020). "Taken together with the report indicating the role of IRS-1 as the inducer of GCK and SREBP-1c, shown in rat hepatocytes and liver-specific IRS-1 knockout mice, persistent expression of IRS-1 and hyperinsulinemia in NAFLD may enhance FAS upregulation in the steatotic liver." (PMID 29717275, 2018). "First, consistent with the ambient postprandial hyperinsulinemia present in MetS mice 1 h after oil gavage, the intestines of these mice, as compared with controls, had much higher levels of phosphorylated AKT, higher mRNA content of the insulin receptor (IR) and insulin receptor substrate 1 (IRS1)." (PMID 26727015, 2016). "Further note, unlike IRS‐1/PI3K, activation of IRS‐2 and IRS‐2/PI3K in both muscle and liver is resistant to downregulation in DIO/MetS/T2DM17, 18, 19, 20 and is responsive to hyperinsulinemia." (PMID 34766133, 2021).
Glucose intolerance (49 papers, 2012 to 2025). Glucose intolerance (GI) can be defined as dysglycemia that comprises both prediabetes and diabetes. "IRS proteins have six isoforms in the family, with its emphasis on IRS1, because IRS1 has wide distributions and its deficiency leads to IR and glucose intolerance." (PMID 31752797, 2019). "The inadvertent over-activation of mTOR also has the potential of tumorigenesis (for example resulting from the loss of tumor suppressor TSC1/2 function, as in Tuberous Sclerosis), but also loss of autophagy function, glucose intolerance via IRS-1 feedback inhibition and learning impairment." (PMID 34215308, 2021). "In well-trained cyclists habituated to a KD, GLUT4 and IRS1 protein contents were decreased in vastus lateralis muscles, which is consistent with the whole-body glucose intolerance found in these athletes." (PMID 38257179, 2024). "Periods of elevated mTOR activity can be detrimental and result in glucose intolerance by inhibiting the insulin receptor substrate 1 (IRS-1)." (PMID 37238686, 2023). "Consistently, ablation of VAPB in mice led to downregulation of IRS-1, suppression of insulin signaling, and glucose intolerance." (PMID 37528084, 2023). "Alpha cell–specific IRS1-knockout mice exhibited glucose intolerance and inappropriate glucagon suppression during glucose tolerance tests." (PMID 33839150, 2021). "Mac-CM, an inflammatory stimulus, induced glucose intolerance accompanied by impaired insulin sensitivity; genistein reversed these changes by restoring the disturbed IRS1 function, leading to an improvement in GLUT4 translocation." (PMID 33255206, 2020). "In the L-TSC1 KO mice, chronic activation of the mTORC1 signal produces a strong inhibitory feedback on insulin receptor substrate 1 (IRS1), which causes a decrease in the AKT signaling pathway, leading to glucose intolerance." (PMID 31835352, 2019). "Overexpression of E3 ligases targeting IRS-1 induces pathological changes such as glucose intolerance or muscle atrophy, as both are under the control of IRS-1-mediated signaling." (PMID 29259227, 2017). "Pin1 enhances insulin-induced IRS-1 tyrosine phosphorylation through its isomerase activity, and Pin1 knockout mice exhibit impaired insulin signaling with glucose intolerance." (PMID 26074875, 2015). "As anessential molecule in insulin signaling, the dysfunction of IRS-1 could decrease downstream insulin effects, thereby contributing to glucose intolerance." (PMID 31195990, 2019). "For instance, knockdown of Irs1 in L6 rat and in primary human myotubes, showed impaired insulin-stimulated glucose uptake; similarly, liver specific Irs1 ablation leads to a marked glucose intolerance." (PMID 30469501, 2018). "Similarly, Par14 enhances insulin-induced IRS-1 tyrosine phosphorylation, and Par14 knockdown exacerbated the glucose intolerance in Pin1 knockout mice." (PMID 26074875, 2015). "Accordingly, there was a corresponding down-regulation of IRS1 and phospho-AKT levels in their liver and skeletal muscle tissues, which correlated with impaired insulin sensitivity and glucose intolerance." (PMID 34574169, 2021). "While glucose intolerance has been observed in S6K1−/− mice, it has also been shown to promote the phosphorylation and feedback inhibition of insulin receptor substrate 1 (IRS1)." (PMID 32054043, 2020). "According to the result showing no change in Irs1 mRNA expression after high fat diet feeding, it was suggested that the level of gene expression was not related to glucose intolerance in skeletal muscle." (PMID 32793459, 2020). "Furthermore, overexpression of SOCS3 decreased the hepatic expressions of IRS1, IRS2 and PI3K, and resulted in glucose intolerance and decrease glucose uptake." (PMID 29743495, 2018). "Moreover, AβOs failed to induce glucose intolerance, hypothalamic IKKβ activation and IRS-1 inhibition in TNFR1−/− mice, or glucose intolerance in mice treated i.c.v. with infliximab." (PMID 25617315, 2015).
Glucose intolerance (continued). "Furthermore, TUDCA ameliorated glucose intolerance possibly through phosphorylation of Akt and AMPK (or ACC), and suppressed phosphorylation of JNK, and IRS-1 (Ser307)." (PMID 23667647, 2013). "It is important to note that although insulin is a potent activator of mTOR through Akt regulatory pathways, mTOR may have a negative feedback loop and led to glucose intolerance through inhibition of the insulin receptor substrate 1 (IRS1)." (PMID 22545721, 2012). "Activation of mTOR promotes the secretion of insulin and increases insulin sensitivity; on the contrary, mTOR may lead to glucose intolerance through blocking of the insulin receptor substrate 1 (IRS1) by phosphorylation of p70S6K in a negative feedback loop manner." (PMID 31080547, 2019).
hepatoma (49 papers, 2006 to 2026). "In hepatoma cells, ghrelin increases IRS-1 associated PI3K activity while inhibits Akt kinase activity." (PMID 24651458, 2014). "In this regard, it is noteworthy that in hepatocellular carcinoma cells, IRS-1 over-expression is associated with increased insulin and IGF-1-stimulated growth and survival signaling, in addition to AAH over-expression relative to the normal liver." (PMID 17156427, 2006). "In addition, miR-183-5p facilitates growth and metastasis of hepatocellular carcinoma cells by targeting IRS1 and is associated with patient survival." (PMID 34692488, 2021). "Because TCF4 (TCF7L2) is one of the major Wnt/β-catenin signaling-associated transcription factors and binds to Irs1 promotor in the rat hepatoma cell line H4IIE16, 21, the effect of dominant-negative TCF4 cDNA (DN-TCF4) on the regulation of Irs1 in primary hepatocytes was examined." (PMID 28710407, 2017). "cAMP responsive element binding protein 3 (CREB3) hinders the progression of hepatocellular carcinoma (HCC) by suppressing the phosphorylation of AKT signaling through binding competitively with insulin receptor substrate 1 (IRS1) to insulin receptor (INSR)." (PMID 38952575, 2024). "Previous studies have also found that miR-183-5p promotes hepatocellular carcinoma progression via regulate IRS1 expression and promotes the invasion and proliferation thyroid cancer cells by regulating FOXO1." (PMID 37548821, 2023). "Previous studies have shown that IRS-1 and 2 are overexpressed in hepatocellular carcinoma (HCC) and pancreatic cancer." (PMID 36900240, 2023). "In hepatoma cells, ROS inhibit IRS1 function in insulin signaling through the induction of IRS1 phosphorylation on Ser307." (PMID 36768755, 2023). "In hepatoma cells, GHS-R activation ameliorates IRS1-associated PI3K activity and suppresses Akt activity." (PMID 35327599, 2022). "Inhibition of NEU1 activity with anti-NEU1 antibody or oseltamivir reduced insulin-stimulated IGF-1R and insulin receptor substrate-1 (IRS-1) phosphorylation in human fibroblasts, and promoted IR-NEU1 association in rat HTC hepatoma cells." (PMID 35479093, 2022). "As previously, evidences have revealed that PYCR1 dramatically enhanced cell growth and survival through activating JNK/IRS1 pathway in the development of hepatocellular cancer." (PMID 34696668, 2021). "The downregulation of PYCR1 dramatically repressed cell growth and survival by inactivating the c-Jun N-terminal kinase/insulin receptor substrate 1 (JNK/IRS1) pathway in hepatocellular cancer cells." (PMID 34696668, 2021). "Another report revealed that the HCV core protein in both transgenic mice or hepatoma cells downregulates IRS1 and IRS2 by upregulating SOCS3." (PMID 33849568, 2021). "MiR-145 has also been shown to target insulin receptor substrate-1 (IRS-1) and impairing insulin-mediated intracellular signaling in hepatic carcinoma." (PMID 33023156, 2020). "The direct exposure of hepatoma cells to LPS moderately decreased insulin receptor substrate 1 (IRS1) expression at 1 hour, whereas FLG increased IRS1 expression at 4 hours (p<0.05 for both)." (PMID 27035341, 2016). "Our current study demonstrates that AFB1 up-regulates IRS2 but down-regulates IRS1 levels in hepatoma cells, leading to a shift in IRS1 and IRS2 expression towards a high IRS2/IRS1 ratio." (PMID 23112878, 2012). "Our focus on insulin and IGF-1 signaling pathways stemmed from earlier studies demonstrating over-expression of AAH in hepatocellular carcinoma cells and in transgenic mice that over-express IRS-1." (PMID 17156427, 2006). "Moreover, overexpression of miR-222 in the murine hepatoma cell line, Hepa 1-6 significantly reduced IRS1 protein levels compared to the controls." (PMID 33197889, 2020). "Notably, we found that miR-27b controls post-transcriptional expression of numerous components of the insulin signaling pathway including the insulin receptor (INSR) and insulin receptor substrate 1 (IRS1) in human hepatoma cells." (PMID 33212990, 2020).